GLS2 (glutaminase 2)
Diseases named in the same sentence as GLS2 in open-access papers (continued):
Sharing a sentence is not in itself a finding about the gene and the disease.
tumor (continued). "Moreover, the overexpression of GLS2 has been proved to have antiproliferative and tumor suppression properties in tumor cells since it also downregulates the PI3K/Akt signaling pathway." (PMID 36914921, 2023). "Therefore, the expression of Il6, Nos2, Ccl2, Spp1, Tnf, Acat2, Aox1, Crem, Gls2, Per3, Pink1, Txnip, and Ypel3 was examined in acidosis upon simultaneous transfection with microRNA mimics or antagomirs in two tumor lines in vitro and in vivo." (PMID 38069241, 2023). "In most tumors, GLS2 serves as a tumor suppressor and GLS1 as an oncogene." (PMID 35310969, 2022). "To investigate GLS1/GLS2 acetylation in murine HCC tumours, we collected mitochondrial lysates from DEN plus CCl4‐induced tumours and adjacent tissues and the acetylation levels of both GLS1 and GLS2 were significantly downregulated in tumours compared with adjacent tissues." (PMID 35538890, 2022). "An accumulation of evidence has shown that GLS1 is overexpressed in multiple malignant and may serve as an oncogene, while GLS2 acts as a tumor suppressor." (PMID 36611819, 2022). "Although HCC has been shown to be a glutamine‐addicted tumour, whether GLS2 contributes to this development is still unclear." (PMID 35538890, 2022). "Furthermore, via negatively regulating the PI3K/AKT pathway, GLS2 was crucial in the tumor suppression of HCC." (PMID 36467089, 2022). "Interestingly, liver–enriched glutaminase 2 (GLS2) appears to play a greater role than ubiquitous and canonical tumour–enriched glutaminase 1 (GLS1) in promoting murine HCC." (PMID 35538890, 2022). "Overall, up-regulation of GLS2 in the low-FRGPI group might be associated with promoting cancer ferroptosis and preventing tumor proliferation." (PMID 35368652, 2022). "On the other hand, GLS2 is either a tumor suppressor or an oncogene, depending on the tumor type." (PMID 33746066, 2021). "In contrast, luminal B tumours showed higher GLS2 expression than luminal A tumours (p = 0.03)." (PMID 34439127, 2021). "It’s reasonable to hypothesize the abnormal of GLS2 could promote the development of tumor through regulating the ferroptotic pathway." (PMID 33602233, 2021). "Hence, it’s easy to understand that the roles of GLS2 are likely to be tumor type-specific, and it enhances the notion that the implication of GLS2 in ferroptosis needs to be carefully interpreted in a context-dependent manner." (PMID 33602233, 2021). "It was demonstrated that in multiple cancer types, higher GLS2 expression was negatively correlated with an EMT signature, which may shed light on the mechanism of tumor suppression by GLS2." (PMID 34573287, 2021). "However, less efforts have been made to target GLS2 due to its controversial roles in tumor suppression." (PMID 33194749, 2020). "Next, we aimed to ascertain whether tumor cells overexpressing GLS2 constitutively (T98G-GAB) or after induction of differentiation by PMA treatment (SH-SY5Y) shift their cellular populations toward cell cycle stages compatible with lower proliferation." (PMID 32042057, 2020). "GLS2 is repressed in many tumor cells and a better understanding of its function in tumorigenesis may further the development of new therapeutic approaches." (PMID 32042057, 2020).
tumor (continued). "Our studies provide evidence for a tumor suppressor role of GLS2 in certain types of cancer." (PMID 32042057, 2020). "Compared with GLS1, GLS2 is more regarded as a tumor suppressor." (PMID 33194749, 2020). "In addition, the expression of glutaminase genes GLS and GLS2 correlates with increased tumor growth rates." (PMID 31801490, 2019). "Consistent with the finding that hypermethylation might be responsible for the downregulation of LEGs, the GLS2 promoter is hypermethylated in tumor tissues." (PMID 30046116, 2018). "Moreover, Gls2 exerts a tumor suppressor function representing a link between amino acid metabolism, ROS scavenging, and inhibition of tumor cells proliferation." (PMID 28467351, 2017). "GLS1 promotes tumor formation, while GLS2 has the opposite effect." (PMID 26751560, 2016). "Interestingly, GLS1 and GLS2 display contrasting functions in tumorigenesis with elusive mechanism; GLS1 promotes tumorigenesis, whereas GLS2 exhibits a tumor-suppressive function." (PMID 26751560, 2016). "Future studies should shed light on the further mechanisms of GLS2 in tumor suppression." (PMID 26751560, 2016). "Although our data support the view that GLS1 is a dominant predictive marker, GLS2 expression within tumor tissues may provide more precise survival information for patients with HCC." (PMID 25844758, 2015). "Therefore, in these patient samples, in addition to the induction of genes related to cell cycle arrest (p21), DCA also stimulated tumor cell metabolism by promoting the expression of AMPKβ1, GLS2 and SCO2." (PMID 26231043, 2015). "We also evaluated the relationship between expression of GLS2 in tumor tissues and survival time." (PMID 25844758, 2015). "Previously, we examined the levels of GLS2 mRNA in a set of primary HCCs at different stages, and found that GLS2 mRNA levels were greatly decreased in majority of primary HCCs compared with normal liver tissues or tumor adjacent liver tissues." (PMID 24797434, 2014). "Considering the critical role of the oncogenic PI3K/AKT signaling in HCC, the negative regulation of the PI3K/AKT signaling by GLS2 could contribute greatly to the tumor suppression activity of GLS2 in HCC." (PMID 24797434, 2014). "Consistent with the results from IHC staining, results from Taqman real-time PCR assays showed that GLS2 mRNA levels were clearly decreased in majority of HCCs; 18 of 21 HCCs showed decreased mRNA levels compared with their matched adjacent non-tumor liver tissues (the cut-off is 2-fold difference)." (PMID 24797434, 2014). "Taken together, these results clearly demonstrated that GLS2 expression is significantly decreased at both mRNA and protein levels in majority of primary HCCs, which strongly suggests a potential important role of GLS2 in tumor suppression of HCC." (PMID 24797434, 2014). "We further investigated whether negative regulation of the PI3K/AKT signaling by GLS2 contributes to GLS2’s role in tumor suppression in HCC." (PMID 24797434, 2014). "Our results demonstrated an important role of GLS2 in tumor suppression in HCC." (PMID 24797434, 2014). "In contrast, in 110 HCC samples in the TMA, 96 HCC samples showed negative for GLS2 (-; 0% positive staining cells), and 10 samples showed weak staining for GLS2 (±), whereas only 4 HCC samples showed positive staining for GLS2 (+) (p<0.0001; HCCs vs. non-tumor liver tissues)." (PMID 24797434, 2014).
tumor (continued). "However, knock-down of GLS2 expression sensitizes cervical cancer to ionizing radiation and thus reduces tumor size through decreasing cellular glutathione and NADH." (PMID 25026281, 2014). "Ectopic expression of GLS2 in tumor cells significantly reduced tumorigenicity." (PMID 23388203, 2013). "Since DNA methylation is a common event in the silencing of tumor suppressor genes, we hypothesized that Gls2 promoter hypermethylation was responsible for its low expression in cancer cells." (PMID 24330717, 2013). "It is still unclear why GLS1 and GLS2 have contrasting roles in tumorigenesis, and furthermore, the mechanism for GLS2 in tumor suppression remains unclear." (PMID 23388203, 2013). "Therefore, it appears that Gls2 is an important tumor suppressor involved in the liver and colon tumorigenesis." (PMID 24330717, 2013). "In addition, GLS2 is an often overlooked role in tumor glutamine metabolism." (PMID 37249801, 2023). "The reason may be that GLS2 can bind to small GTPase Rac1 and inhibit its interaction with the Rac1 activator guanine nucleotide exchange factor, which in turn inhibits Rac1 and thus favoring the suppression of tumor metastasis." (PMID 35310969, 2022). "The results strongly suggest that GLS2 upregulation has tumor suppression activity and could help to rewire cellular metabolism toward a normal non-proliferative phenotype, providing a new strategy to combat some types of cancer where GLS2 is frequently silenced." (PMID 32042057, 2020). "Moreover, upregulation of GLS2 was also evident in mitochondria; hence, the tumor suppressive effects elicited by GLS2 overexpression might involve mitochondrial and nuclear contributions." (PMID 32042057, 2020). "Indeed, some studies have reported that tumor tissues from radioresistant patients exhibit significantly higher GLS2 levels than those from radiosensitive patients and that apoptosis, in response to radiation, is increased in GLS2-knockdown cancer cells." (PMID 31027222, 2019). "In addition to Rac1, GLS2 may interact with other proteins to regulate their functions, which in turn contributes to GLS2’s function in tumor suppression." (PMID 26751560, 2016). "We further investigated whether GLS2 plays a role in tumor suppression in HCC." (PMID 24797434, 2014). "In contrast, GLS2 is downregulated in HCC and inhibits tumor growth by negatively regulating the PI3K/AKT signaling pathway." (PMID 40370433, 2025). "By 120 weeks of age, all Gls2 knockout mice included in the experiment developed either B-cell lymphomas, HCC, or both tumor types." (PMID 38067269, 2023). "A subsequent functional analysis revealed that GLS2 negatively regulates the PI3K/AKT signaling pathway, which contributes to the tumor-suppressive properties exerted by GLS2 in HCC." (PMID 38067269, 2023). "Normal hepatocytes preferentially express GLS2, whereas, during HCC development, a MYC-dependent metabolic switch from GLS2 to GLS1 occurs and sustains the rewiring of glutamine metabolism in tumor cells." (PMID 37108625, 2023). "In oesophageal squamous cell carcinoma, GLS2, as an intermediate molecule, is regulated by the methylation of METTL3, which eventually promotes tumour cell metastasis." (PMID 37829798, 2023). "Efficient inhibition or genetic silencing of GLS1 in different tumor models has validated GLS1 as a therapeutic target, making it a better target for glutaminolysis inhibition than GLS2." (PMID 36831355, 2023).
tumor (continued). "Taken together, these results indicated that GCN5L1 protein levels decreased in murine HCC cells and tumours, and the regulation of GLS1 and GLS2 needs to be addressed further during the development of HCC." (PMID 35538890, 2022). "We then analysed the correlation of tumour glutaminase activity with the expression of GLS1, GLS2, GCN5L1, c‐Myc and two major glutamine transporters downstream of c‐Myc, which are known to activate mTORC1 in HCC specimens." (PMID 35538890, 2022). "GLN uptake promoted both GLS and GLS2 mRNA expression after 6 h of stimulation, which promoted the use of GLN by tumor cells while stimulating downstream mTOR signaling to promote tumor progression." (PMID 34503536, 2021). "Upregulated expression of SLC7A11 (10/14), SLC1A5 (7/14), SLC7A5 (6/14), and SLC3A2 (5/14) was observed in most of the tumor tissues; however, GLS in LUSC, KIRC, and KICH and GLS2 in KIRC and LIHC, were significantly downregulated." (PMID 34573287, 2021). "Consistently, all the six DEGs (GLS2, ASS1, FOLH1B, AGXT2, CPS1, and GPT2) enriched in “arginine biosynthesis” in our results were significantly downregulated in tumor hepatic tissue from HBV-infected patients compared with adjacent nontumor tissues." (PMID 32775402, 2020). "The researches revealed that GLS2 negatively regulates the PI3K/AKT signaling and plays an important role in tumor suppression in HCC." (PMID 33194749, 2020). "The three proteasome inhibitors which downregulated MYC expression in HLRCC tumor cells, also decreased the expression of GLS and GLS2." (PMID 31804603, 2019). "In this study, we further investigate the impact of DUOX1, GLS2 and FBP1 genes expression on liver patients’prognosis after tumor resection." (PMID 27079415, 2016). "In order to determine the model robustness for predicting prognosis of HCC patient after tumor resection, we finally resorted to ROC curve analyses by individually using the expression of each marker (DUOX1, GLS2, FBP1)." (PMID 27079415, 2016). "Taken together, these results indicate that GLS2 is preferentially expressed in normal hepatocytes, but in HCC tumor cells GLS1 expression is upregulated and GLS2 expression is downregulated." (PMID 25844758, 2015). "Our results further showed that GLS2 plays an important role in tumor suppression in HCC, and the negative regulation of the PI3K/AKT signaling by GLS2 contributes greatly to the function of GLS2 in tumor suppression in HCC." (PMID 24797434, 2014). "IHC staining results showed that in 125 non-tumor liver samples in the TMA, 118 samples showed positive staining for GLS2 (+; ≥10% positive staining cells) and 7 samples showed weak staining for GLS2 (±; <10% positive staining cells)." (PMID 24797434, 2014). "However, other molecular mechanisms responsible for Gls2 as a tumor suppressor remain unknown." (PMID 24330717, 2013).
tumor (continued). "Yet another protein that interacts with GLS2, at least in HCC cells, is Ras-related C3 botulinum toxin substrate 1 (Rac1), a member of the Rho GTPase family, involved in the regulation of tumor angiogenesis, invasion, and metastasis; these processes underlie malignant transformation." (PMID 38067269, 2023). "Second, GLS2 can promote the maturation of miR-34a by binding and stabilising Dicer and inhibiting the epithelial-mesenchymal transition (EMT) molecule Snail in an activity-dependent manner via miR-34a and glutamine, thus inhibiting tumour metastasis." (PMID 37829798, 2023). "The GLS1 gene is overexpressed in many tumor cell lines and primary tumors, while the GLS2 gene is not widely expressed in tumors." (PMID 36831355, 2023). "Low proliferative, but not high proliferative, luminal tumours also showed a weak positive correlation between GLS2 protein and c-MYC (p < 0.001), SLC1A5 (p < 0.05) and SLC3A2 (p < 0.001)." (PMID 34439127, 2021). "However, FANCD2, SLC7A11, GLS2, DPP4, and ALOX15 were obviously suppressed in grades 1–3 of tumor samples compared to normal tissues." (PMID 34531924, 2021). "GLS2, which is an important enzyme in conversion of glutamine to glutamate, and thereby a regulator of glutathione (GSH) synthesis, is upregulated in tumor cells at low pH." (PMID 33407762, 2021). "In general, GLS1 shows a positive regulation of EMT process while the functions of GLS2 on EMT are diverse and may be attributed to different tumor types as well as varying degrees of tumor malignancy." (PMID 33194749, 2020). "Worth mentioning that none of the HCC cells used in this study express GLS2, which would be an advantage to the tumor cells, since it has been recently proposed that GLS2 exhibits a tumor suppressive function." (PMID 28970582, 2017). "According to the results of Fisher’s exact test and computational model (MLP and discriminant analysis), ultimately, Cox multivariate regression analysis was performed included the factors such as DUOX1, GLS2, FBP1, age, intrahepatic metastasis, tumor stage, histological grade and HBsAg." (PMID 27079415, 2016). "Although, DUOX1, GLS2 and FBP1 acts as liver tumor suppressor and mechanisms about tumor inhibiting of the three genes have been studied, the specific associations between prognosis of liver patients and expression of these three genes still remains unknown." (PMID 27079415, 2016). "Intensive GLS2 staining (++) was observed in 77.9% (67/86) of adjacent non-tumor tissues, and was observed in 20.9% (18/86) of tumor tissues." (PMID 25844758, 2015). "We found that the patients exhibiting GLS2 expression (+/++) in tumor tissues had a significantly prolonged survival time (35.60 months vs. 24.37 months) compared to patients without tumor GLS2 expression." (PMID 25844758, 2015). "Our results further showed that the promoter region of GLS2 is hypermethylated in a high percentage of HCCs but not in their matched adjacent non-tumor liver tissues." (PMID 24797434, 2014).